GZMB (granzyme B)
Diseases named in the same sentence as GZMB in open-access papers (continued):
Sharing a sentence is not in itself a finding about the gene and the disease.
breast cancer (continued). "We examined the effects of MEPB on NK cells-IFN-γ, perforin, and granzyme B cytotoxicity against MDA-MB-231 breast cancer cells by ELISA method and apoptosis assay." (PMID 39619199, 2024). "The METABRIC data analyses showed that low expression of GZMB was significantly associated with poor patient survival, as was ING4-low expression, in the basal subtype of breast cancer." (PMID 38968186, 2024). "This approach has been evidenced using mesothelin-specific CAR-T-cell-derived EVs against breast cancer cells, mediating the killing of tumor cells in vitro and in vivo by the expression of perforin and granzyme B." (PMID 37175226, 2023). "GZMB, known for stimulating anti-tumor immune responses and inhibit tumor growth, is correlated with favorable prognosis in breast cancer tissues." (PMID 38111587, 2023). "For example, after breast cancer cells encounter NK cells, actin accumulates at the immune synapses, which in turn limits the accumulation of the cytotoxic molecule granzyme B (GrzB) in cancer cells." (PMID 36032170, 2022). "The description of a truncated FGFR1 (also referred to as nFGFR1) as a result of Granzyme B, was described in breast cancer cells and claimed to affect gene expression that altered cell behavior such as invasion." (PMID 35906694, 2022). "Murine pDCs activated with IMQ or CpG express and release TRAIL and Granzyme B, and they elicit antitumor responses against breast cancer in vitro and in vivo." (PMID 36232698, 2022). "The results showed that in breast cancer population, the frequencies of Granzyme B (GZMB)+CD8+T cells and GZMB+DNT cells in CA were lower than those in PB, while the frequencies of PD1+CD8+T cells and PD1+DNT cells were higher than those in PB." (PMID 35894707, 2022). "For example, hypoxic breast cancer cells exhibit an increased autophagic flux resulting in superior granzyme B (GZMB) degradation." (PMID 36319998, 2022). "Paclitaxel made tumor cells more sensitive to CTL-mediated cytotoxicity in a mouse model of breast cancer by increasing the permeability of granzyme B by perforin-independent CTLs." (PMID 34638242, 2021). "In line with this, one study reported a mechanism by which ER+ breast cancer tumor cells from breast cancer treated with estrogen upregulated the granzyme B inhibitor proteinase inhibitor-9 (PI-9), which suppresses CD8+ T cell cytotoxic activity." (PMID 34944786, 2021). "TIL B cells isolated from breast cancer tissues have been reported to express granzyme B and exhibited in vitro cytotoxic activity toward breast cancer cells." (PMID 33193299, 2020). "To further study the relationship between MSN and immune response, we analyzed MSN and GZMB expression in breast cancer samples from The Cancer Genome Atlas database." (PMID 32941674, 2020). "Breast cancer cells in hypoxic conditions were able to evade NK cell killing via the activation of autophagy and the subsequent degradation of granzyme B in vitro." (PMID 32745353, 2020). "Accordingly, GZMB degradation was boosted by activation of autophagy in hypoxic human breast cancer cells." (PMID 32466293, 2020). "Cytokine release assays were performed to quantify the relative amounts of IFN‐γ, granzyme B, and perforin in the co‐cultured systems between NK cells (transduced or non‐transduced) and breast cancer cells (TNBC and non‐TNBC cells)." (PMID 32592435, 2020).
breast cancer (continued). "Here, we demonstrate that miR-519a-3p confers resistance to apoptosis induced by TRAIL, FasL and granzyme B/perforin by interfering with apoptosis signaling in breast cancer cells." (PMID 28771222, 2017). "Granzyme B is found to be expressed in breast carcinomas and thought to be either protective or work as an immune regulator." (PMID 28603578, 2017). "We demonstrated in vitro that the NK-derived serine protease granzyme B (GZMB) was selectively degraded into autophagosomes in hypoxic breast cancer cells, in which autophagy is induced." (PMID 27917371, 2016). "Further, we also found that MDA-7/IL-24 mounted an antitumor immune response by increasing levels of infiltrating CD8+ T cells and the frequency of IFN-γ or granzyme B-producing CD8+ T cells in the mammary tumors." (PMID 26474456, 2015). "In addition, the role of GZMB in the tumor microenvironment is of great significance for breast cancer immunotherapy." (PMID 40860340, 2025). "Furthermore, hypoxia-induced autophagy contributes to the degradation of GZMB, reducing the sensitivity of breast cancer cells to NK-mediated cell lysis." (PMID 40303301, 2025). "Ing4-deleted mouse mammary tumors contained a significantly reduced number of GzmB+CD4+ T cells." (PMID 38968186, 2024). "Aqueous ginseng extract has demonstrated an essential role in NK cell-mediated cytotoxicity through IFN-γ activation, while thymoquinone isolation from Nigella sativa increased NK cell cytotoxicity against MCF-7 breast cancer cells by expressing perforin, granzyme B, and IFN-α." (PMID 39619199, 2024). "Specifically, NK-EVs primed with IL-15 have demonstrated remarkable cytotoxic activity against various human cancers such as glioblastoma and breast cancer through increasing the expression of apoptotic molecules (e.g., perforin, granzyme B, FasL, and caspases)." (PMID 37484408, 2023). "Our results indicate that GZMB may serve as a biomarker for predicting treatment response and prognosis for advanced breast cancer." (PMID 37760424, 2023). "In breast cancer immunotherapy, the role of GZMB in the tumor microenvironment is also important." (PMID 37760424, 2023). "Therefore, the results in TCGA cohort demonstrated that GZMA, GZMB, and IFNG in the low-risk group were highly expressed, while TGFB1 was elevated in high-risk breast cancer patients (p < 0.001)." (PMID 35619902, 2022). "GZMB was identified as a progression biomarker in basal-like breast cancer." (PMID 35432539, 2022). "In vitro studies demonstrated that breast cancer cells under hypoxic conditions could evade NK cells killing by enzymatic degradation of granzyme B." (PMID 35912261, 2022). "A third study found that high autophagy levels in breast cancer cells promoted NK cell-derived granzyme B degradation, suggesting that this mechanism could contribute to the resistance to CTL killing." (PMID 35379808, 2022). "In conclusion, a novel fusion protein MICA-G129R was created and demonstrated able to bind to PRLR-positive breast cancer cells and NK cells, promote the release of granzyme B and IFN-γ by NK cells and enhance the cytotoxicity to PRLR-positive breast cancer cells." (PMID 34077462, 2021). "Of note, the strongest correlation of ERβ with CD8A and GZMB was observed in breast cancer." (PMID 33462142, 2021). "We demonstrated that the MICA-G129R fusion protein not only binds to human natural killer NK-92 cells and PRLR-positive human breast cancer T-47D cells, but also promotes NK cells to release granzyme B and IFN-γ and enhances the cytotoxicity of NK cells specifically on PRLR-positive cells." (PMID 34077462, 2021).
breast cancer (continued). "Interestingly, GZMB expression has been reported in cancer cells from diverse solid tumors, such as breast cancer, head and neck cancer, and lung carcinoma, where it has been suggested to intervene in extracellular matrix remodeling, promoting EMT." (PMID 32466293, 2020). "Further, NK cell cytotoxic killing of breast cancer cells is diminished by hypoxia through secreted factors that impair NK cell development and tumor cell activation of autophagy that leads to degradation of granzyme B (GZMB) in autophagosomes." (PMID 31535086, 2019). "Interestingly, breast cancer cells were partially protected from the NK-mediated cytotoxicity following CM (CFSElow population represents apoptotic cells), consistent with lower levels of toxic granzyme B incorporation." (PMID 35256052, 2022). "Moreover, GSDME (DFNA5) can be cleaved by granzyme B (GzmB) to activate pyroptosis and stimulate tumor-associated macrophages, tumor-infiltrating natural-killer and CD8+ T lymphocytes to evoke anti-tumor immunity in breast cancer." (PMID 36090993, 2022). "Moreover, we found that cytotoxicity against MDA-MB-231 breast cancer cells was associated with an increase in granzyme B and perforin B. such effect was not obtained in the MCF-7 cancer cell line co-cultured with PBMC." (PMID 34440813, 2021). "Similarly, the up-regulation of PCNA, CHECK1 or GZMB might be related to other aspects of apoptosis or breast cancer pathways." (PMID 31825969, 2019). "Previous efforts in developing EMP2-targeting therapies, such as the granzyme B fusion protein GrB-Fc-KS49, have demonstrated promising therapeutic potential for targeted breast cancer treatment." (PMID 41173824, 2025). "Accordingly, CARTs secreted more IFN-γ, TNF-α, granzyme B and expressed more CD25, CD107a than blank-T cells when exposed to PDAC-CAFs, HCC-CAFs and PFs/breast cancer CAFs/colorectal cancer CAFs." (PMID 39086477, 2024). "Indicators of apoptosis in breast cancer include circulating soluble FASL, granzyme B, and cytochrome C, which increase following treatment." (PMID 39132504, 2024). "These supported the tumor suppressive roles for granzyme B and ING4 in the basal subtype breast cancer." (PMID 38968186, 2024). "Co-culture experiments demonstrated that NK cells induced apoptosis in MDA-MB-231 breast cancer cells in the presence of MEPB by increasing perforin, granzyme B, and IFN-γ expression in both healthy donors and breast cancer patients-experimental groups." (PMID 39619199, 2024). "On the other hand, the level of perforin, granzyme B, and IFN-γ in breast cancer patients-experimental groups were increased compared to that of healthy experimental groups." (PMID 39619199, 2024). "The level of IFN-γ, perforin, and granzyme B by NK cells were significantly elevated after being treated with MEPB (Group 4), leading to increase apoptosis on MDA-MB-231 breast cancer cells." (PMID 39619199, 2024). "The combination of these two drugs promoted the secretion of granzyme B (GZMB) by CD8+ T cells and enhanced the killing effect of TILs cells in breast cancer cells." (PMID 37554324, 2023). "In an orthotopic mammary tumor model, CD8 + T cells displayed increased production of granzyme B, IL-2, and TNF-a at higher doses of CIRT while high-dose photon therapy did not induce secretion of these cytokines from CD8 + tumor-infiltrating lymphocytes." (PMID 36138265, 2023). "The progression of breast cancer is characterized by increased immune cell infiltration in tumor parenchyma and stroma, including CD4+ and CD8+ granzyme B+ cytotoxic T cells, B cells, macrophages and dendritic cells." (PMID 35953532, 2022). "Strong cytotoxicity in breast cancer MDA‐MB‐231‐Luc and MCF‐7‐Luc cell lines by releasing cytokines, perforin, and granzyme B (in vitro). inhibition of tumour growth at a late stage in mice bearing MDA‐MB‐231 TNBC xenografts (in vivo)." (PMID 35762299, 2022).
breast cancer (continued). "Compared with a human mammary epithelial cell line MCF-10A, the expression levels of GSDMC, GZMB and IL18 were upregulated, while TP63 was found with lower expression level in breast cancer cells SK-BR-3, BT-549, MCF-7, and MDA-MB-231 using RT-qPCR assay." (PMID 36936274, 2022). "RBMS1 ablation significantly reduced PD-L1 level, thus to stimulate CD8+ CTL population and Granzyme B release and enhance the T-cell-mediated cancer cell killing, suggesting that RBMS1 plays an important role in breast cancer immunotherapy regulation." (PMID 35538152, 2022). "As shown, compared with MCF-10A, the expression levels of GSDMC, GZMB and IL18 were upregulated, while TP63 was found with lower expression level in breast cancer cells SK-BR-3, BT-549, MCF-7, and MDA-MB-231 (P < 0.05)." (PMID 36936274, 2022). "Meanwhile, SB203580, an inhibitor of p38 MAPK pathway, blocked the increased MICA/B expression of LA-pulsed DCs, and the increased secretion of perforin, granzyme-B, IFN-γ, as well as cytotoxicity of LA/DC-induced NK cells against breast cancer." (PMID 33910591, 2021). "Nonetheless, in mouse models of breast cancer, activated pDC can directly kill tumor cells through TNF-related apoptosis inducing ligand (TRAIL) and granzyme B (GzmB) as well as they jumpstart activation of CTL and NK cells." (PMID 33859645, 2021). "Both expression levels of cleaved-caspase-3/pro-caspase-3 and granzyme B in tumor tissues were significantly elevated when theacrine was supplemented, indicating the induction of programmed cell death in tumor cells might be involved in the attenuation of mammary carcinoma." (PMID 34946538, 2021). "The transcriptional levels of GZMB, LCP2, and SELL were significantly upregulated, whereas GIMAP7 was significantly downregulated, in breast cancer compared with normal breast tissue." (PMID 33042828, 2020). "Recently, an interesting study reported that activated pDCs were able to kill 4T1 breast cancer cells through TRAIL and granzyme B death-initiating molecules." (PMID 32138292, 2020). "Our research demonstrates that activated pDCs can kill breast cancer cells in vitro through TNF-related apoptosis-inducing ligand (TRAIL) and Granzyme B. In our experiments IMQ was more effective than CpG." (PMID 28052019, 2017). "And we found that most Granzyme B+ CD103+ CD8+ Trm cells infiltrating within TLS rather than non-TLS one in breast cancer." (PMID 39926286, 2025). "Overall, kidney and breast cancers displayed the highest expression of GZMA, GZMB, GZMK and PRF1." (PMID 40002821, 2025). "In a HER2(+) breast cancer model, HER2-CAR T cells upregulated PD-1 after incubation with target cells, and the PD-1 blockade did increase CAR T cell proliferation, IFN-γ production, and granzyme B expression in vitro while enhancing in vivo cytotoxicity." (PMID 37569894, 2023). "We found that the frequencies of Granzyme B (GZMB)+CD8+T and GZMB+DNT cells in cancer tissues (CA) of breast cancer were lower than those in blood samples of patients (PB), and the frequencies of programmed cell death protein 1 (PD1)+CD8+T and PD1+DNT cells in CA were higher than those in PB." (PMID 35894707, 2022). "The combination therapy initiates a pro-inflammatory anti-tumour response that is subsequently exhausted (no detectable Granzyme B+ cells and influx of Treg cells) in mammary tumours." (PMID 34290237, 2021). "The TRM phenotype in breast cancer with a high expression of co-inhibitory receptors and high expression of GZMB is remarkably similar to the phenotype attributed to late dysfunctional (or "exhausted") T cells, suggesting that TRM in breast cancer are dysfunctional." (PMID 33467084, 2021). "Moreover, we also found clear reporter cleavage showing granzyme B and caspase-8 activity in HeLa and MDA-MB-468 breast carcinoma cells with activated primary NK cells as effector cells." (PMID 30135688, 2018).
breast cancer (continued). "Moreover, miR-519a-3p decreases NK cell-mediated killing of breast cancer cells by downregulating tumor cell ligands for the NK cell-activating receptor NKG2D and conferring resistance toward granzyme B- as well as TRAIL-induced apoptosis." (PMID 28771222, 2017). "One study reported ZNF331 expression in T cell clusters in breast cancer with resident effector memory phenotype co-expressing regulatory elements that may involve in cell cycle regulation and upregulating GZMK over GZMB and PRF1, aligning with our observations." (PMID 40028342, 2025). "The low levels of Granzyme B and TRAIL produced by steady-state pDCs increase considerably after activation, and it has been proven that TLR-activated pDCs have the ability to kill several tumor-derived cell lines, including hematological cancer cells, breast cancer cells, and melanoma cells." (PMID 36232698, 2022). "Furthermore, in a murine breast cancer model, a cancer vaccine therapy employing the systemic delivery of a tumor-targeting Salmonella-based STAT3 shRNA increased the proliferation and granzyme B levels of intratumoral CD4+ and CD8+ T cells, which favored the destruction of malignant cells." (PMID 29115974, 2017). "To assess the generalizability and specificity of this finding, we analyzed GZMB expression in a large, non-IBC-specific breast cancer cohort (TCGA-BRCA, n=1079)." (PMID 41567210, 2025).